ZNF69 (zinc finger protein 69)
Description:
May be involved in transcriptional regulation.
Synonyms: Cos5; hZNF3
Tractability: PROTAC: ubiquitination databases record sites on it.
Gene: Protein-coding gene on chromosome 19 (11,887,782 to 11,914,329, forward strand). Ensembl gene ENSG00000198429.
Subcellular location: Nucleus
Subcellular location (Human Protein Atlas): Nucleoplasm
Gene Ontology:
Molecular function: protein binding; DNA-binding transcription factor activity, RNA polymerase II-specific; RNA polymerase II transcription regulatory region sequence-specific DNA binding
Biological process: regulation of transcription by RNA polymerase II; regulation of DNA-templated transcription
Cellular component: nucleus
Genetic constraint (gnomAD): Loss-of-function variants: 47 observed, 52.71 expected, observed/expected ratio (o/e) 0.89, 90% interval 0.7 to 1.14. The upper end of that interval is the gene's LOEUF score, 1.14, which puts it in group 4 of 6, group 1 being the genes least tolerant of losing a copy. Missense variants: 717 observed, 701.12 expected, observed/expected ratio (o/e) 1.02, 90% interval 0.96 to 1.09. Synonymous variants: 216 observed, 230.91 expected, observed/expected ratio (o/e) 0.94, 90% interval 0.84 to 1.05.
Homologues: Orthologues: chimpanzee ZNF69 (98% identical), mouse Zfp78 (32% identical), Drosophila melanogaster CG3281 (22% identical), Drosophila melanogaster CG2712 (20% identical), Drosophila melanogaster Phs (19% identical). Paralogues in human: ZNF440 (80% identical), ZNF439 (73% identical), ZNF20 (58% identical), ZNF763 (54% identical), ZNF491 (49% identical), ZNF555 (46% identical), ZNF560 (40% identical), ZNF778 (39% identical), ZNF77 (38% identical), ZNF596 (37% identical), ZNF599 (36% identical), ZNF266 (36% identical), and 50 more.
Diseases named in the same sentence as ZNF69 in open-access papers:
ZNF69 is named in the same sentence as 5 diseases in open-access papers, as found by Europe PMC text mining. Sharing a sentence is not in itself a finding about the gene and the disease. The quoted sentences say what the papers report.
diabetes (1 paper, 2010). "Recently, the zinc finger protein 69 (Zfp69) gene was identified as a candidate for the diabetes QTL of Nidd/SJL." (PMID 21167066, 2010).
Down syndrome (1 paper, 2024). "Altered methylation of the Zinc Finger Protein 69 (ZNF69) gene has been suggested to play a role in neurogenesis and brain development in Down syndrome." (PMID 39367879, 2024).
cancer (1 paper, 2021). A tumor composed of atypical neoplastic, often pleomorphic cells that invade other tissues. "Genes whose upregulation is associated with some cancers (TMEM140, ANXA10, ZNF69, CA9, LOXL2, PAGE3, ELFN1) were also on this list, as was a putative tumor suppressor (DEC1)." (PMID 33601339, 2021).
ZNF69 also shares sentences with these, for which no sentence is quoted: hypopharyngeal carcinoma (1 paper); tumor (1).